LINC00663 (long independently transcribed non-coding RNA 663)
Synonyms: MGC39821
Gene: Long non-coding RNA gene on chromosome 19 (19,749,637 to 19,776,434, reverse strand). Ensembl gene ENSG00000266904.
Diseases named in the same sentence as LINC00663 in open-access papers:
LINC00663 is named in the same sentence as 11 diseases in open-access papers, as found by Europe PMC text mining. Sharing a sentence is not in itself a finding about the gene and the disease. The quoted sentences say what the papers report.
pancreatic cancer (3 papers, 2022 to 2025). "More importantly, LINC00663 was highly expressed in pancreatic cancer and served as a prognostic biomarker of pancreatic cancer." (PMID 39219375, 2024). "Further screening identified five pancreatic cancer-specific epi-lncRNA genes (AL161431.1, LINC00663, LINC00941, SNHG10, and TM4SF1-AS1), which were used to construct a prognostic model." (PMID 40264765, 2025). "The results showed that AL161431.1, LINC00663, LINC00941, and SNHG10 were highly expressed in pancreatic cancers samples; in particular, AL161431.1 and LINC00663 had significantly higher levels." (PMID 35647035, 2022). "Additionally, LINC00663 expression is low in DU-145 and PC3 prostate cancer, HGC-27 stomach carcinoma, CRL-1469 pancreatic carcinoma, A549 lung cancer, MCF7 breast cancer, and BCPAP thyroid cancer cell lines." (PMID 35647035, 2022).
breast carcinoma (2 papers, 2021 to 2022). "Then, we determined five lncRNAs with a putative role in breast cancer using the LncRNA disease (v.3.0) database, including AC144450.1, APTR, RAMP2-AS1, LINC00663, and ZNF337-AS1." (PMID 34094972, 2021).
glioma (2 papers, 2022 to 2024). A benign or malignant brain and spinal cord tumor that arises from glial cells (astrocytes, oligodendrocytes, ependymal cells). "The expression of LINC00663 in glioma tissues and cell lines is higher as compared to the normal brain tissues and human astrocytes." (PMID 35647035, 2022). "Also, LINC00663 was reported to be highly expressed in glioma, and LINC00663 knockdown could restrain cell viability by modulating AKT/mTOR pathway." (PMID 39219375, 2024).
bladder cancer (1 paper, 2024). "This study is to elucidate the effect of the LINC00663/EBF1/NR2F1 axis on inflammation and angiogenesis in bladder cancer (BC) and related molecular mechanisms." (PMID 39219375, 2024).
Hepatic fibrosis (1 paper, 2023). The presence of excessive fibrous connective tissue in the liver. "Together, these results identified an important regulatory axis whereby LINC00663 that was regulated by FOXA1 sponged hsa-miR-3916 and regulated SF2-FN alternative splicing expression in cholestatic liver fibrosis." (PMID 36672150, 2023).
tumor (2 papers, 2024). "LINC00663 was detected to be overexpressed, and silencing LINC00663 resulted in inhibited inflammation and angiogenesis in xenograft tumours formed by 5637 BC cells." (PMID 39219375, 2024). "However, overexpression of NR2F1 nullified the inhibitory effect of LINC00663 knockdown on tumour growth (#p < 0.05)." (PMID 39219375, 2024). "The co-regulation of LINC00857, LINC00968, LINC00663, and ITGA9-AS1 on SOX2 suggested their potential contributions in aberrant sialylation process during tumor progression." (PMID 38632255, 2024).
LINC00663 also shares sentences with these, for which no sentence is quoted: cancer (1 paper); lung carcinoma (1); prostate carcinoma (1); stomach carcinoma (1); thyroid cancer (1).